TLR4 (toll like receptor 4)
Diseases named in the same sentence as TLR4 in open-access papers (continued):
Sharing a sentence is not in itself a finding about the gene and the disease.
COVID-19 (continued). "In this sense, a small study analyzed PBMCs transcriptomics in patients with COVID-19 and observed that the expression of TLR4 and downstream signaling molecules were significantly upregulated." (PMID 33859644, 2021). "TLR4 downstream signaling molecules and inflammasome-related proteins were found to be upregulated in the blood cells from COVID-19 and PD patients." (PMID 34281186, 2021). "Previous reports suggest that the TLR pathway, specifically TLR4, is associated with SARS-CoV-2 transmission and COVID-19 severity by activating the hyper-inflammation process." (PMID 34067609, 2021). "While the Δct of PGRP-4 exhibited a strong correlation (rs = 0.65) with the viral load, that of TLR-4 exhibited a moderate correlation (rs = 0.44) with the ct value of CoV2 in COVID-19 saliva." (PMID 34707585, 2021). "When comparing COVID-19 MILD and COVID-19 SEVERE groups, a decreased expression of TLR3, accompanied by a deficient IFN-γ and an enhanced TLR4 expression were associated with an unfavorable outcome." (PMID 34315957, 2021). "Even though experimental evidence confirming the interaction between the S protein and TLRs is lacking, the main cytokines involved in patients with severe COVID-19 are products of TLR4 viral signaling: IL-6 and TNF-α." (PMID 34975904, 2021). "Clinical observations revealed their upregulation in COVID-19 patients as well as during hemolytic events, which highlights even more the TLR4 signaling pathway in both situations." (PMID 33925394, 2021). "Specifically, the involvement of the TLR4 signaling pathway in mediating the virus entry, as well as the massive immune and inflammatory response in COVID-19 patients is explored." (PMID 34281186, 2021). "Data indicate that the toll-like receptor-4, peptidoglycan recognition protein, and sACE2 are elevated in COVID-19 saliva and correlate moderately with the viral load." (PMID 34707585, 2021). "Platelet TLR4 also has an important role in thrombosis, thus potentially linking toll-receptor expression to the hypercoagulability observed in COVID-19 patients." (PMID 34030677, 2021). "Both IL-6 and TNF-α are known to be the main cytokines involved in severe symptoms’ onset in COVID-19 patients, and to be downstream of the TLR4 signalling pathway." (PMID 34564408, 2021). "It is noteworthy that TLR4-mediated inflammatory signaling is upregulated in COVID-19 patients and this is regulated by zinc." (PMID 34468306, 2021). "We believe that the hyperactivation of TLR4 induced by gut microbiota products, translocated into the circulation, strongly contributes to the cytokine storm, worsening the prognosis of COVID-19 in the elderly, diabetic and hypertensive individuals." (PMID 34458281, 2021). "On the other hand, TLR3 mRNA was decreased, while TLR4 mRNA was increased in the COVID-19 SEVERE group when compared to the COVID-19 MILD group." (PMID 34315957, 2021). "In the present study, we also found high expression of both TLR2 and TLR4 genes in peripheral blood leukocytes of severe COVID-19 cases." (PMID 33345622, 2021). "Several authors have suggested clinical trials to test TLR4 antagonists in the treatment of severe COVID-19." (PMID 34564326, 2021). "One study reported upregulation of TLR4 and its downstream signaling mediators in COVID-19 patients." (PMID 34248968, 2021). "Our observations of higher TLR-4 transcript in the saliva of COVID-19 patients is in alignment with its potential role as a receptor for SARS-CoV2." (PMID 34707585, 2021). "We observed markedly elevated cytokine responses in COVID-19 patients upon Toll-like receptor 4 (TLR4) activation by lipopolysaccharide (LPS) and TLR7/8 activation by R848." (PMID 33377122, 2020). "COVID-19 patients upregulate TLR4 pro-inflammatory signaling, as TLR4 is most likely responsible for recognizing molecular patterns from SARS-CoV-2." (PMID 33352889, 2020).
COVID-19 (continued). "Out of 22 eligible articles that investigated candidate genes (2 as associated with COVID-19), the top-ranked genes in the number of studies were ACE2, CLEC4M (L-SIGN), MBL, MxA (n = 3), ACE, CD209, FCER2, OAS-1, TLR4, TNF-α (n = 2)." (PMID 32917282, 2020). "Moreover, LPS-induced surface expression of TLR-4 and COVID-19 S1 protein-induced MMP-9-related gelatinolysis were abrogated by benzydamine under the high-glucose condition." (PMID 41756532, 2026). "Another PRR that has gained prominence in the context of long COVID-19 is Toll-like receptor 4 (TLR4), which plays an essential role in the antibacterial response by detecting the lipopolysaccharide (LPS) molecule of Gram-negative bacteria but is also involved in viral recognition." (PMID 41346576, 2025). "It has been shown that TLR4-mediated chronic inflammatory responses lead to an imbalance in the proportions of alveolar macrophages and CD163+ myeloid-derived monocyte-macrophages, which represents one of the fatal mechanisms underlying COVID-19 pathogenesis." (PMID 41293166, 2025). "Similarly, for COVID-19, TLR4 triggers an excessive inflammatory response, exacerbating severe acute respiratory syndrome coronavirus 2 (SARS-CoV-2) spiking protein-mediated lung injury, thereby deteriorating COVID-19." (PMID 41411324, 2025). "First, we evaluated whether PMN-MDSC from COVID-19 patients express TLR4 and found that this receptor is present on the PMN-MDSC surface." (PMID 41322987, 2025). "Therefore, the current consensus leans toward an indirect mechanism for TLR4 activation in severe COVID-19." (PMID 41176818, 2025). "Moreover, patients with severe COVID-19 exhibit pathological phenotypes such as over-activation of the TLR4/NF-κB pathway, vascular endothelial damage, and lymphocyte depletion." (PMID 41411324, 2025). "Our results suggest that the TLR1, TLR4, TLR6, and TLR10 variants may influence the outcome during corticoid treatment in COVID-19 patients." (PMID 40149530, 2025). "This highlights the importance of timing and context in TLR4-targeted treatments for COVID-19." (PMID 41011507, 2025). "Our results indicate that PMN-MDSC are involved in the pathogenesis of COVID-19 not only by impairing adaptive immune response; indeed, the Spike-TLR4-induced ET could contribute to the downstream inflammatory pathways, damaging pulmonary epithelial cells." (PMID 41322987, 2025). "A previous study also showed that activation of TLR4 is closely related to inflammation and immune hyperactivation, suggesting that targeting TLR4 could effectively reduce inflammation in severe COVID-19 patients." (PMID 39627184, 2024). "The impact of TLR4 in the pathogenies of COVID-19 has been demonstrated in multiple studies." (PMID 38791489, 2024). "Finally, SARS-CoV-2-induced myocarditis and multiple-organ damage was correlated to TLR4 activation and hyperinflammation in COVID-19 patients." (PMID 38791489, 2024). "Interestingly, an aptamer blocking SARS-CoV-2 spike–TLR4 interaction selectively inhibits SARS-CoV-2-induced inflammation, strongly suggesting that, in addition to TRL2, TLR4 should be considered a biochemical target for COVID-19 therapy." (PMID 39770027, 2024). "Specifically, exon 2 and 3 of TLR4 displayed higher inclusion levels in COVID-19 patients." (PMID 38414855, 2024). "Importantly, both TLR3 and TLR4 are known to recognize RNA viruses and trigger NF-kB-mediated proinflammatory responses, contributing to the severity of COVID-19 (59, –, 61)." (PMID 38078754, 2024). "Various studies have addressed the role of TLR4 in the pathogenicity of COVID-19." (PMID 38791489, 2024). "This study highlighted miR-4485-3p/TLR4 axis might provide a therapeutic direction for anti-osteoporosis therapy in patients with a prior infection of COVID-19." (PMID 38504994, 2024). "Moreover, other studies have shown that TLR4 expression, which, according to the results of our study, is activated mainly by Nucleocapsid, is correlated with severe COVID-19." (PMID 38807115, 2024).
COVID-19 (continued). "In conclusion, this study revealed that IL-6R, TLR4, TLR2, and IFNG may be potential pathogenic genes in the CRS associated with COVID-19." (PMID 38165854, 2024). "We concluded that TLR-7 and TLR-4 agonists may be effective adjuvants in COVID-19 vaccines for mounting immunity that is long-lasting against SARS-CoV-2 infection." (PMID 38543837, 2024). "Targeting TNF-α/IFN-γ in combination with TLR4 may represent a promising therapeutic approach for alleviating CRS in individuals with COVID-19." (PMID 39359733, 2024). "IL6R, TLR4, TLR2, and IFNG may be potential pathogenic genes and therapeutic targets for the CRS associated with COVID-19." (PMID 38165854, 2024). "Our in silico findings detected two residues, Asn233 and Asn281, binding to TLR4, suggesting that these residues may participate in the immunomodulatory mechanism of bLf observed in the activation of NK and T cells during COVID-19." (PMID 39483459, 2024). "It has been shown that S100A8 is responsible for the induction of an aberrant neutrophil subset in pathogenesis of COVID-19 through stimulating the TLR4 signaling, which are thought to induce cytokine storm or excessive inflammation, as is observed in severe COVID-19 cases." (PMID 39350339, 2024). "Among the AS forms of TLR4, the inclusion of exon 2 or exon 3 has been reported to be elevated in LPS treated cells, mirroring our observation of increased inclusion of these exons in COVID-19 patients." (PMID 38414855, 2024). "Moreover, studies have shown that the TLR4 expression levels are significantly higher in the peripheral blood neutrophils and monocytes of severe COVID-19 patients than in healthy controls." (PMID 38165854, 2024). "Furthermore, TLR-4 was up-regulated in lung macrophages in a subgroup of deceased COVID-19 patients." (PMID 37686069, 2023). "Furthermore, serum TLR4 concentrations increased in previously infected COVID-19-positive men than women; these data confirm that PTX3 was strongly linked with the hyperactivation of the TLR4 pathway." (PMID 37762499, 2023). "Blocking Spike-TLR4 interaction could therefore be a potential target for regulating excessive inflammatory responses in COVID-19 patients." (PMID 37175768, 2023). "Our finding that hypoxic monocytes produce elevated chemokine ISG levels upon SARS-CoV-2 infection in a TLR4- and cholesterol-dependent manner might open new therapeutic opportunities to prevent systemic progression of severe COVID-19 cases." (PMID 37377965, 2023). "Importantly, a monoclonal antibody blocking TLR4 was recently shown to reduce mortality at 28 days in severe COVID-19 by 66.0 % when compared to placebo on top of standard of care." (PMID 38034686, 2023). "TLR-4 was strongly up-regulated in damaged pneumocytes in a subgroup of deceased COVID-19 patients." (PMID 37686069, 2023). "Several TLRs, such as TLR2, TLR3, TLR4 and TLR7, have been associated with COVID-19 severity." (PMID 37175768, 2023). "Therefore, we propose that, following COVID-19 vaccination, these monocytes are activated by TLR4 through direct spike protein activation, with induced transcriptional activity upregulating epigenetic enzymes to methylate cytoplasmic ACE2." (PMID 37369668, 2023). "POP inhibition could reduce aggregation of alpha-synuclein in neurons, hence, investigating anti-COVID agent(s) against TLR-4 and POP might help in alleviating neurological complications linked with COVID-19." (PMID 36985442, 2023). "TLR4 activation by SARS-CoV-2 infection has been suggested to increase surface ACE2 expression to facilitate viral entry and contribute to hyperinflammation to cause multi-organ failure in severe COVID-19 patients." (PMID 37369668, 2023). "Data show that TLR-4 expression induces a persistent activation of the inflammation, with inefficient resolution, and pathological macrophage shift, thus explaining one of the mechanisms of lethal COVID-19." (PMID 37686069, 2023).
COVID-19 (continued). "Furthermore, scRNA-seq analysis unveiled significant immune dysregulation in COVID-19 patients, characterized by altered immune cell proportions, phenotypic shifts, enhanced cell-cell communication, and elevated TLR4 and ABCA1 in CD16 monocytes." (PMID 38022594, 2023). "The hyperinflammatory response instigated by TLR4 activation may provide a plausible rationale for AMI occurrences in COVID-19 patients." (PMID 38022594, 2023). "TLR4 contributes to the immune response and pathogenesis of COVID-19, and thus, TLR4 could be a therapeutic target in COVID-19." (PMID 36899824, 2023). "In MIS-C and KD, as in severe COVID-19, the additional synergisms are due to receptors associated with bacterial antigen activation, particularly TLR2 and TLR4, and are consistent with high observed rates of bacterial co-infections in severe COVID-19 patients who develop MIS-C (Introduction)." (PMID 36769320, 2023). "Moreover, calprotectin levels were also associated with thrombotic events in COVID-19 patients probably due to engagement of calprotectin with RAGE and TLR4 by activation of these innate immune sensors." (PMID 37248708, 2023). "TLR2, TLR3, TLR4 and TLR7 have been associated with COVID-19 severity." (PMID 37175768, 2023). "Our current study concluded that, miR-20a, IL-10 and TLR4 are potential biomarkers for severity of COVID-19 disease and also blockade of IL-10 and TLR4 may constitute a novel therapy for COVID-19 patients." (PMID 36864077, 2023). "TLR4 may have a pathological role in COVID-19 inflammation, our data and other data published to date do not indicate a similar role in MIS-C." (PMID 37777557, 2023). "Since COVID-19 patients admitted to intensive care units frequently present bacterial superinfections with massive TLR4 stimulation, and because cell death and tissue damage during the infection favors TLR4 activation, we also mimicked TLR4 activation in monocytes through LPS stimulation." (PMID 35592335, 2022). "Notably, a Japanese pharmaceutical company is participating in collaborative COVID-19 clinical trials to test the efficacy of a TLR4 antagonist, Eritoran (E5564), in reducing cytokine storm." (PMID 36246240, 2022). "The involvement of another TLR, i.e., TLR4 in the pathogenies of COVID-19 has been shown." (PMID 35682644, 2022). "In this review, we aim to discuss the anti-inflammatory effects of irisin, focusing on the MAPK, AMPK, and TLR4/MyD88 intracellular pathways, and examine how exercise-induced irisin may improve the outcomes of inflammatory conditions, such as COVID-19." (PMID 35784579, 2022). "Moreover, semaP3A/NRP-1 pathway is required for TLR4 activation, which plays an integral role in the development of immunological disturbances during COVID-19 and AIS." (PMID 36009579, 2022). "MB, TLR4 and ALB are involved in coronavirus biology, and are associated with COVID-19 prognosis." (PMID 36275701, 2022). "Toll-like receptor 4 (TLR-4) appears to be one such connecting link, as the spike protein of SARS-CoV-2 (the COVID-19 causative agent) could bind with equal efficacy with ACE-2 (angiotensin-converting enzyme 2) and TLR-4 receptors of dopaminergic neurons." (PMID 35888166, 2022). "Interestingly, major cytokines like IL-6 and TNF-α involved in the severe COVID-19 cases are the downstream products of the TLR4 signaling pathway." (PMID 35812188, 2022). "TLR4, is one of the ‘fate-deciding’ regulators of immunity and COVID-19 immunopathogenesis." (PMID 35869117, 2022). "Therefore, many TLR4 modulators, both natural and synthetic, can be investigated in the context of COVID-19 treatment." (PMID 35832809, 2022). "Moreover, the semaP3A/NRP-1 pathway is required for the activation of toll-like receptor 4 (TLR4), which plays an integral role in the development of immunological disturbances during COVID-19." (PMID 36009579, 2022).
COVID-19 (continued). "Additionally, TLR4/7/8-activated peripheral myeloid cells from patients with moderate to severe COVID-19 produced less IFNβ and more proinflammatory cytokines and had higher PD-L1 expression than healthy control cells." (PMID 36085197, 2022). "Both TLR3 and TLR4-mediated pro-inflammatory responses contribute to the severity of COVID-19." (PMID 35356515, 2022). "Based on the evidence presented in this review, targeting TLR4 could be effective in treating COVID-19." (PMID 33505220, 2021). "The crosstalk between RAGE and TLR4 in response to DAMPs is underlined by the fact that RAGE-positive, TLR4 KO peritoneal macrophages produced almost no proinflammatory cytokines in response to HMGB1, suggesting the existence of a HMGB1/RAGE/TLR4 axis in mediating inflammation in COVID-19." (PMID 34204735, 2021). "In conclusion, patients suffering from MAFLD could suffer a chronic stimulation of TLR7/8 and TLR4 in the alveolar macrophages, which make them more vulnerable to severe COVID-19." (PMID 33859644, 2021). "Additionally, the heat shock protein HSP5a (also known as GRP78), a marker for endoplasmic reticulum stress and the TLR2/TLR4 activator, is released at unusually high concentrations in severe COVID-19 patients." (PMID 33672738, 2021). "Indeed, HMGB1-RAGE/TLR4 signaling is believed to mediate endothelial activation and dysfunction in COVID-19 conditions." (PMID 34204735, 2021). "TLR4 antagonist given in the later severe stages of COVID-19 could mitigate against the aberrant excessive TLR4 stimulation that may lead to a cytokine storm." (PMID 33505220, 2021). "HMGB1 triggers toll-like receptor-4, generating the release of pro-inflammatory cytokine including IL-6, which is one of pathophysiological hallmarks of the cytokine storm in critically ill COVID-19 patients." (PMID 33939645, 2021). "The overexpression of TLR4 in PD and in COVID-19 patients together with high levels of many other inflammatory mediators could explain the link between these diseases." (PMID 34281186, 2021). "Here we assessed the expression of TLR-2, TLR-4, and peptidoglycan recognition protein (PGRP)-4 and evaluated the association of changes in these markers as it related to SARS-COV-2 infection in the saliva of hospitalized patients with COVID-19." (PMID 34707585, 2021). "A further reason for thinking that there are likely to be as-yet-unidentified negative feedback systems antagonizing NOD2 and that the antagonistic effects of NOD2 on TLR4 are important in severe COVID-19 is that the interferon (IFN) function is very severely impaired." (PMID 33672738, 2021). "This review highlights a potential role of TLR4 in SARS-CoV-2 entry mechanisms and the subsequent severe inflammatory complications with a focus on injury to the lungs and heart, since they are the major causes of mortality from COVID-19." (PMID 33505220, 2021). "Given the role of the TLR4/HMGB1 axis in the progression of pulmonary inflammation—including with cytokine storms occurring with COVID-19—our results indicate that leytragin is a promising therapeutic agent for the prevention of cytokine storm with COVID-19." (PMID 34616852, 2021). "Given its dual antiviral effects and TLR4 antagonism, as well as being a natural compound, it may be a promising candidate in the treatment of COVID-19." (PMID 33505220, 2021). "For CVD + CKD + COVID-19, the targets were C3, TLR4, MAPK14, and CYBB." (PMID 34067609, 2021). "In addition, Naltrexone, an approved opioid antagonist, is being repurposed for COVID-19 as TLR4 antagonist." (PMID 34696490, 2021). "The mechanism by which SARS-CoV-2 induces HMGB1 release in COVID-19 remains unknown, although new evidence suggests that toll-like receptor 4 (TLR4) signaling may play a role in this process." (PMID 34616852, 2021).